IRF4 (interferon regulatory factor 4)
Diseases named in the same sentence as IRF4 in open-access papers (continued):
Sharing a sentence is not in itself a finding about the gene and the disease.
viral infection (17 papers, 2014 to 2025). "Severe viral infection predisposition was seen in 3 patients (POLR3A, IFIH1, TLR7XL) and bacterial susceptibility in 3 others (IRF4, IFNGR1, NCSTN)." (PMID 41209815, 2025). "DEGs related to M2 differential polarization, like Irf4 showed up regulation at 24 hpi., the late term after viral infection." (PMID 38992966, 2025). "Mechanistically, host cell-released lipids during viral infection are presented by lung infiltrating CD1d+ B-1a cells to activate IL-17A production in γδ T cells via γδTCR-mediated IRF4-dependent transcription." (PMID 33772013, 2021). "At D12 post-infection, WT and Irf4+/fl had similar levels of virus in their sera, whereas Irf4fl/fl mice showed slightly reduced control of the virus infection." (PMID 26714260, 2015). "Consistent with our previous finding that M2stop infected mice have a defect in virus infection in plasma cells, we now show that this defect is likely due to a significant defect in the frequency of virus infected B cells expressing IRF4." (PMID 24391506, 2014). "In contrast, mice lacking IRF4 in CD11c+ cells show a significant reduction of CD301b+ cDC2s in both lung and lung‐dLN upon viral infection despite the normal number of the total lung cDC2s, suggesting a context‐dependent requirement of IRF4 for their development." (PMID 41201234, 2025). "Thus, robust expression of IRF4 is important for maximal CD8+ T cell expansion in response to acute viral infections." (PMID 26714260, 2015). "As a result, we focused on understanding how modest reductions, rather than a complete loss of IRF4 expression, impacted the protective response to persistent virus infection." (PMID 26714260, 2015). "While modest reductions in the levels of IRF4 were inconsequential for early control of virus replication through d26 p.i., long-term studies revealed that Irf4+/fl mice had a defect in controlling the persistent virus infection." (PMID 26714260, 2015). "Together, these results suggest that IRF4 plays a role in subverting multiple immune surveillance mechanisms by the transcriptional control of related genes, including PD-L1 and PD1, and cGAS and STING, in the context of oncogenic viral infection that is associated with blood cancers." (PMID 40733503, 2025). "This protein is activated by TLRs during the immune response and regulates gene expression in response to cytokines, stress, and bacterial or viral infections, as well as notably the IFN regulatory factors (IRFs, particularly IRF3, IRF4, and IRF8)." (PMID 40665467, 2025). "As summarized in this review, Tfh cell-related transcription factors including Bcl6, IRF4, STAT1/STAT4/STAT5, T-bet, TCF-1, LEF-1, TOX2, Bach2, FOXP1, and KLF2 are all involved in the virus infection." (PMID 32766317, 2020). "In a previous study investigating the impact of IRF4 downregulation on the functionality and expansion of CD8+ T cells during acute viral infections, CD8+ T cells with downregulated IRF4 levels exhibited CD27 upregulation and superior functionality as compared to wild type T cells." (PMID 37287982, 2023). "Interferon Regulatory Factor 4 (IRF4) is essential for driving effector differentiation, as genetic deletion of Irf4 results in a failure of the expansion phase in the CD8+ T cell response to viral infection." (PMID 33371448, 2020). "KSHV derived PAN RNA was proved in to interact with histone H1/H2A, single-stranded binding proteins (SSBPs) and interferon regulatory factor 4 (IRF4) in infected cells to decrease the expression of IFNγ, IFNα, interleukin-18, and RNase L to facilitate viral infection in primate cell lines." (PMID 30740112, 2018). "At D8 post-infection, Irf4+/fl and Irf4fl/fl mice had reduced proportions and numbers of virus-specific CD8+ T cells compared to WT mice, consistent with previous studies of acute virus infections in these mice)." (PMID 26714260, 2015).
asthma (16 papers, 2016 to 2025). "rs9391997 is a 3’ UTR variant in IRF4 associated with childhood-onset asthma, type 1 diabetes, autoimmune thyroid disease, and chronic lymphocytic leukaemia (CLL)." (PMID 39241920, 2024). "Recently, our study found that methyl CpG binding domain protein 2-mediated Th17 differentiation in severe asthma is associated with IRF4 and SOCS3 expression, providing novel insight into epigenetic regulation and target for treatment in severe asthma." (PMID 34566492, 2021). "Overexpression of Foxp2 in an asthma model inhibited Th9 differentiation and reduced IRF4 and BATF expression." (PMID 40909266, 2025). "STAT3 is a known effector of PM; IRF4 is also known for its function in Asthma by activating Th17 through regulation of chromatin accessibility but not for the role in response to PM exposure." (PMID 32448264, 2020). "We found that both IRF4 and IL-17 had a significantly increased expression in the lung and the spleen cells of severe asthma model mice." (PMID 28808358, 2017). "This indicates that MBD2 can participate in the differentiation of Th17 cells and IL-17 secretion through IRF4 expression and so participate in the pathogenesis of the neutrophil-predominant severe asthma model." (PMID 28808358, 2017). "Also, in the lungs of animals treated with allergen in order to induce either experimental asthma or tolerance, we found an additional cDC population (Cluster 6) which expressed Irf8, Batf3 as well as low levels of Irf4, Sirpa and Itgam." (PMID 37251386, 2023). "We also established an HDM-induced asthma model with WT, p38αΔDC, IRF4ΔDC and IRF4/p38αΔDC mice." (PMID 35551270, 2022). "This shows that MBD2 can affect IRF4 expression in severe asthma." (PMID 28808358, 2017). "So, IRF4 is therefore an important factor in neutrophil-predominant severe asthma." (PMID 28808358, 2017). "Next, we needed to analyze whether MBD2 can affect IRF4 and participate in asthma." (PMID 28808358, 2017). "Furthermore, mice with IRF4 knockdown in mast cells or mice administered with sialostatin L showed a strong reduction in eosinophilia and airway hyperresponsiveness, important symptoms of asthma." (PMID 28611951, 2017). "Less clear is the mechanism behind childhood asthma loci such as 6p25.3 near IRF4 and 17q21.32 near TBX21, which we associate here with CRSwNP but not asthma." (PMID 41213931, 2025). "Moreover, a significant changes of several cytokines related to Th9 cell differentiation in mouse asthma model was detected compared with the control mice group, including forkhead box O1(FOXO1), IL-4, IL-9, IRF4, Spi1, BATF, and IRF1." (PMID 36253857, 2022). "At present, there is little research on the role of MBD2 in severe asthma, and the relationship between MBD2 and IRF4 in severe asthma is not known." (PMID 28808358, 2017).
autoimmune disease (16 papers, 2013 to 2025). A disorder resulting from loss of function or tissue destruction of an organ or multiple organs, arising from humoral or cellular immune responses of the individual to their own tissue constituents. "In patients with autoimmune diseases, abnormality of Foxp3 expression resulted in IRF4-deficiency, which caused incapable of starting the transcription of downstream gene and impaired immunosuppressive function of Treg cells." (PMID 31380412, 2019). "IRF4 plays a role in the initiation and progression of autoimmune diseases such as celiac disease and is strongly associated with human pigmentation traits." (PMID 29771307, 2018). "The IRF4-deficient T cells exhibit reduced capacity to induce expansion of T-helper subsets that cause autoimmune disease, suggesting that an intrinsic function of IRF4 in CD4+ T cells may be to sustain robust proinflammatory responses required to confer protection from pathogen." (PMID 33803441, 2021). "Since these cells are crucial to the pathogenesis of autoimmune diseases, IRF4 possibly facilitates the initiation and progression of autoimmune diseases." (PMID 35350715, 2022). "Although studies of Irf4 knockout mice indicate skewing of T-helper subsets from Th1 and Th17 towards Th2, few studies have examined intrinsic and extrinsic functions of IRF4 produced by T cells in T cell-mediated autoimmune diseases such as uveitis." (PMID 33803441, 2021). "In the present study, we went further by defining gene signatures related to the type I IFN signature and IRF4 expression, which were differentially used by different autoimmune diseases." (PMID 30666255, 2018). "Previous studies have highlighted a role for IRF4 in the pathogenesis of autoimmune diseases in mouse and humans." (PMID 30340504, 2018). "Treg-specific deletions of IRF4 and Cbfβ resulted in Th2-type inflammatory diseases such as lymphoproliferation, autoimmune disease in the lung and skin, and hyperproduction of IgE." (PMID 24058613, 2013). "Therefore, eliminating IRF4 has been shown to impede tumor growth, enhance treatment for autoimmune disease, and promote organ graft tolerance." (PMID 39481080, 2024). "BACH2 dysregulation may also confer disease vulnerability, including autoimmune diseases, by inducing IRF4 protein accumulation as well as the chromatin dissociation of PU.1 in B cells." (PMID 38605225, 2024). "Moreover, IRF4 participates in autoimmune diseases such as systemic lupus erythematosus and rheumatoid arthritis." (PMID 37495990, 2023). "We therefore generated mice lacking irf4 in T cells (CD4-IRF4KO) and investigated whether expression of IRF4 by T cells is also required for regulating T cells that suppress autoimmune diseases." (PMID 33803441, 2021). "We therefore used the EAU model, an autoimmune disease confined to the immune privileged neuroretina, to investigate whether expression of IRF4 is necessary for the development of organ-specific autoimmune diseases mediated by T cells." (PMID 33803441, 2021). "To investigate whether expression of IRF4 by T cells contributes to mechanisms of T cell differentiation and immune regulation during an autoimmune disease, we generated mice with targeted deletion of irf4 in CD4+ T cells (CD4-IRF4KO)." (PMID 33803441, 2021). "Our findings provide further support that IRF4 could be a potential therapeutic target for autoimmune diseases such as RA where anti-IL-6 is effective." (PMID 30340504, 2018). "The abnormal expression of Foxp3 could result in IRF4 missing, resulting in unable to start the transcription of downstream gene and compromise the immunosuppressive function of Treg cells in patients with autoimmune diseases." (PMID 31380412, 2019). "Finally, data on IRF4 expression was analyzed in other autoimmune diseases." (PMID 30666255, 2018). "IRF4 has been found to facilitate the infiltration of CD8+ T cells, advancing both tumors and autoimmune diseases." (PMID 39481080, 2024).
autoimmune disease (continued). "The role of IRF4 or IRF8 in lymphocyte development and effector functions suggest that they are potential therapeutic targets for modulating immune responses during autoimmune diseases." (PMID 33803441, 2021). "IRF4 deletion in mice may induce transplant acceptance by establishing CD4+ T-cells dysfunction and render mice resistant to several autoimmune diseases, such as ulcerative colitis and experimental autoimmune encephalomyelitis." (PMID 36505471, 2022). "We previously tested whether genes coregulated by the “Th17 core” (RORC, STAT3, BATF, IRF4, and MAF) were enriched for gene sets from GWAS of nine autoimmune diseases and three “negative controls” (Alzheimer's, schizophrenia, and type 2 diabetes)." (PMID 30696696, 2019).
chronic lymphocytic leukemia (15 papers, 2012 to 2025). "There are known associations between the IRF4 gene and several diseases, such as rhinitis and chronic lymphocytic leukemia." (PMID 23537197, 2013). "Interferon regulatory factor 4 (IRF4) is a transcription factor essential for the development of T helper 2 (Th2), Th17 and Th9 cells, and the rs872071 variant in its 3-prime untranslated region is a susceptibility locus for chronic lymphocytic leukemia." (PMID 28344652, 2017). "However, another report found that expression of IRF4 was associated with a poor prognosis for B-cell chronic lymphocytic leukemia (CLL)/small lymphocytic lymphoma (SLL)." (PMID 23342264, 2012). "For example, elevated IRF4 expression has been linked to an immunosuppressive TME that favors follicular lymphoma progression, whereas diminished IRF4 levels impair immune surveillance and facilitate tumor progression in chronic lymphocytic leukemia." (PMID 40733503, 2025). "Exceptional LBCL, IRF4+ cases with CD5 or CD23 expression need to be distinguished from prolymphocytic progression or large cell transformation of chronic lymphocytic leukemia/small lymphocytic lymphoma." (PMID 37081786, 2023). "In contrast to its essential survival function in activated DLBCLs, IRF4 also serves as an important tumor suppressor that inhibits the development of another type of B-cell malignancy, chronic lymphocytic leukemia (CLL)." (PMID 35472072, 2022). "Regarding IRF4, the SNP we have investigated, rs872071 A > G, is located in the 3′UTR of the gene and has been associated with increased risk for chronic lymphocytic leukemia and Hodgkin lymphoma, suggesting that it might also be a risk factor in other haematological diseases." (PMID 28083618, 2016).
colitis (14 papers, 2016 to 2025). Inflammation of the colon. "Given the crucial role of ILC3-derived cytokines in infection-induced colitis, particularly IL-22-mediated clearance of Citrobacter rodentium, we evaluated the consequences of IRF4 deficiency during bacterial challenge." (PMID 40585371, 2025). "Nevertheless, impaired development of colon LP cDC2 in IRF4 conditionally depleted mice was associated with a delayed onset of T cell-dependent colitis which suggested a role for IRF4-expressing cDC2 in the initial priming of colitogenic T cells." (PMID 36189323, 2022). "In line with that, T cell restricted IRF4-deficiency severely compromised T cells’ ability to induce colitis." (PMID 33584655, 2020). "Employing the CD4+CD25− naïve T cell transfer model, we found that T cells fail to elicit colitis in IRF4-deficient compared to IRF4-proficient Rag1−/− mice." (PMID 33584655, 2020). "A TLR4/NF‐κB/IRF4 signaling pathway is indispensable for M. elsdenii‐mediated DC activation and thereby leads to the augment of colonic Th1 and Th17 inflammation, resulting in an exacerbation of colitis‐associated tumorigenesis." (PMID 40801433, 2025). "In addition, the development of TNBS-induced colitis is markedly suppressed in mice overexpressing IRF4, whose effects are associated with the downregulation of NF-κB-dependent proinflammatory cytokine responses." (PMID 39403381, 2024). "IRF4 promotes IL-17 expression in mucosal tissues through direct binding to the IL-17 promoter, thereby modulating Th17-mediated colitis." (PMID 40585371, 2025). "Female mice with a deletion of GBP5 are more resistant to developing colitis than their wild-type littermates, showing higher colonic IRF4 phosphorylation." (PMID 38531874, 2024). "Our collective findings would suggest that the concerted role of GBP5 and IRF4 extends beyond the response to FMT to a larger role in the development of colitis; however, further studies are required to confirm this." (PMID 38531874, 2024). "Intriguingly, IRF4 expression has also been previously shown to be upregulated in patients with UC and to play a role in experimental colitis in mice." (PMID 38531874, 2024). "In support, we found that genetic deletion of GBP5 protected mice from colitis when they were compared to their wild-type littermates, and additionally IRF4 phosphorylation was dysregulated in their colonic tissue." (PMID 38531874, 2024). "The results identify a role for GBP5, and potentially IRF4, in the establishment of colitis in mice." (PMID 38531874, 2024). "These previous studies showed that in vivo cross-regulation and protection from colitis is abrogated in IRF4-deficient mice and NOD2 activation facilitates IRF4-mediated de-ubiquitination of key factors necessary for NF-κB activation." (PMID 36189261, 2022). "Here, with the help of novel genetic model systems, future studies need to decipher cell-type specific roles of IRF4 within ontogenetically distinct cDC and monocyte-derived cell populations in the context of colitis." (PMID 33584655, 2020). "Thereby, this data set was suitable to help define the T cell-extrinsic role of IRF4 in the context of colitis." (PMID 33584655, 2020). "In the context of colitis, a T cell-intrinsic role of IRF4 in driving immune-mediated gut pathology is established." (PMID 33584655, 2020). "Supporting this concept, in TNBS-induced colitis, IRF4 is required for (acute) colitis induction but suppresses chronic inflammation in the chronic disease phase." (PMID 31632388, 2019). "However, caution should be exercised regarding the clinical application of IRF4 activation in IBD, as IRF4 expressed in CD4+ T cells mediates the development of Th17-dependent experimental colitis." (PMID 39403381, 2024). "Finally, these previous studies showed that administration of IRF4 plasmid embedded in an HVJ-E envelope causes IRF4 expression in intestinal cells and inhibition of TNBS-colitis." (PMID 36189261, 2022).